FGL1 (fibrinogen like 1)
Diseases named in the same sentence as FGL1 in open-access papers (continued):
Sharing a sentence is not in itself a finding about the gene and the disease.
steatosis (2 papers, 2022 to 2025). Increased lipid within the cytoplasm of cells. "Our results are in line with a recent study showing that whole‐body Fgl1 knockout developed a more pronounced steatosis than their WT counterparts when fed a high‐fat diet for 16 weeks or a methionine‐choline deficient (MCD) diet for 3 weeks." (PMID 40832769, 2025). "The present work supports the most recent studies suggesting that FGL1 may exert a protective function during the progression of steatosis, but its exact contribution and the mechanism regulating Fgl1 expression during metabolic alterations are still unknown." (PMID 40832769, 2025). "Importantly, we found that Fgl1 expression was significantly increased after 4 weeks on a western diet (i.e., during the onset of the steatosis) and subsequently reduced after 6–8 weeks when the steatosis progressed." (PMID 40832769, 2025). "The same group also used lentiviral vectors or short‐hairpin RNA to show that, in mice fed a high‐fat diet for 12 weeks, overexpression of FGL1 increased hepatic lipid accumulation and NAFLD score, whereas its knockdown reduced the steatosis and the NAS score." (PMID 40832769, 2025).
viral hepatitis (2 papers, 2024 to 2025). An acute or chronic inflammation of the liver parenchyma caused by viruses. "Additionally, FGL1 has demonstrated potential as a disease biomarker in radiation and drug-induced liver injury as well as HCC, while FGL2 shows promise as a biomarker in viral hepatitis and liver transplantation." (PMID 38816776, 2024).
acute liver failure (1 paper, 2013). Rapid deterioration of liver function causing encephalopathy and coagulopathy. "In animals with acute liver failure, administration of recombinant Fgl1 results in decreased mortality supporting the notion that Fgl1 stimulates hepatocyte proliferation and/or protects hepatocytes from injury." (PMID 23483972, 2013).
Aortic dissection (1 paper, 2022). Aortic dissection refers to a tear in the intimal layer of the aorta causing a separation between the intima and the medial layers of the aorta. "Nine proteins (Lumican, FGL1, PI16, MMP9, FBN1, MMP2, VWF, MMRN1, and PF4) related to the pathogenesis of aortic dissection were identified by David /Ease and String techniques as candidate biomarkers for verification test." (PMID 35910577, 2022).
Ascites (1 paper, 2025). Accumulation of fluid in the peritoneal cavity (between the layers of the peritoneum that lines the abdomen). "A possible but speculative explanation is that the Child-Pugh score more accurately captures features of acute disease deterioration in AH, such as ascites and hepatic encephalopathy, and therefore is associated with the acute phase protein FGL-1." (PMID 39553834, 2025).
Chronic Lymphocytic Leukemia (1 paper, 2025). "The Chronic Lymphocytic Leukemia (Broad, Nature 2015) RNAseq dataset was analysed using the cBioPortal in regard to the expression of class II HLA genes and the conventional LAG-3 ligands: FGL1, LGALS3." (PMID 40136700, 2025).
Fulminant hepatic failure (1 paper, 2020). Hepatic failure refers to the inability of the liver to perform its normal synthetic and metabolic functions, which can result in coagulopathy and alteration in the mental status of a previously healthy individual. "FGL1 accelerates hepatocyte proliferation and protects against liver injury by activating the EGFR/ERK cascade through the Src-dependent pathway, exhibiting its potential to be used to treat fulminant hepatic failure in humans." (PMID 33123164, 2020).
Hypertension (1 paper, 2021). The presence of chronic increased pressure in the systemic arterial system. "The results of blood pressure and urinary protein analysis showed that FGL1 treatment significantly reduced L-NAME-induced hypertension and proteinuria, which is consistent with our hypothesis." (PMID 34957095, 2021).
ischemic stroke (1 paper, 2014). A stroke disorder caused by obstruction of blood flow to the brain, due to thrombotic (local blood clot formation) or embolic (due to a blood clot or other material traveling from another site) event. "In addition, given prior links between variants associated with D-dimer levels and stroke, we utilized the same Mendelian randomization approach as for LPA above and found a nominally significant association between FGL1 c.545_546insA and increased risk of ischemic stroke (OR = 1.32, P = 0.024)." (PMID 25078778, 2014).
liver cirrhosis (1 paper, 2025). "Conversely, high FGL1 expression was significantly associated with larger tumor size and liver cirrhosis." (PMID 40832769, 2025).
liver failure (1 paper, 2013). A liver disease characterized by the liver losing or has lost all of its function. "Previous studies on Fgl1 have focused primarily on its role in hepatocyte biology, showing that the protein is secreted by hepatocytes, enhances tritiated thymidine incorporation into hepatocytes, and rescues animals from liver failure." (PMID 23483972, 2013).
mastitis (1 paper, 2025). Inflammation of breast tissue during lactation or postpartum due to an obstructed duct or infection. "Bta-miR-2285aj-5p appears to induce mastitis by activating the ERK1/2 and NF-κB pathways, leading to the positive regulation of SPDYA and FGL1." (PMID 39795030, 2025).
metastasis (1 paper, 2023). The spread or migration of cancer cells from one part of the body (where they first appeared) to another. "Additionally, higher plasma FGL1 levels were correlated with diminished OS in CRC or GC patients with liver metastasis." (PMID 37872170, 2023).
migraine (1 paper, 2025). "Six proteins were significantly upregulated in migraine with a >1.5 fold change compared to controls and Padj < 0.05 (FAM3C, GOLM1, PSA7, ENPP2, DSG2, TFRC); 3 proteins were significantly downregulated (FGL1, CAH2, AMYP)." (PMID 40852402, 2025).
necrosis (1 paper, 2022). The phenotypic observation that death has occurred in groups of cells or in one or more tissues due to external factors, such as infection, toxins, mechanical trauma, loss of blood supply and other injuries (e.g. corrosion or burning). "In the current study, we aim to investigate the clinical benefits of FGL-1 in predicting the severity of AP and infected pancreatic necrosis (IPN), which can improve the diagnostic efficiency of AP." (PMID 36556955, 2022).
pancreatic ductal adenocarcinoma (1 paper, 2022). An infiltrating adenocarcinoma that arises from the epithelial cells of the pancreas. "FGL1 was also shown to be associated with cell-cycle regulation in pancreatic ductal adenocarcinoma (PDAC), as the downregulation of FGL1 promotes the arrest at the G2/M cell cycle and the expression of Cyclin B1, inhibiting the growth of tumor cells." (PMID 36358792, 2022).
rhabdomyosarcoma (1 paper, 2025). A rare aggressive malignant mesenchymal neoplasm arising from skeletal muscle. "At the same time, downregulation of innate immune effectors, including neutrophil defensins (DEFA1/3), and fibrinogen-like protein 1 (FGL1), along with various immunoglobulin chains, might be the cause of impaired antigen presentation and immune surveillance in rhabdomyosarcoma." (PMID 40710368, 2025).
schizophrenia (1 paper, 2014). A major psychotic disorder characterized by abnormalities in the perception or expression of reality. "In schizophrenia-coagulation network, the SCZCGs including F8, FN1 and FGL1 are differential expressed candidate genes which are associated with coagulation function." (PMID 25522158, 2014).
tumor (133 papers, 2016 to 2026). "In vivo assays revealed that treatment with Lag-3 antibodies negated the tumor growth enhancement associated with Dcdc2 overexpression, while Fgl1 knockdown blocked the efficacy of Lag-3 antibodies." (PMID 40533767, 2025). "Conversely, increased HCC tumor growth induced by diethylnitrosamine was observed in Fgl1-deficient mice compared with control wild-type mice." (PMID 38973608, 2024). "FGL1 loss is associated with tumor dedifferentiation and increased Akt pathway signaling in HCC and is probably an effect independent of antitumor immunity." (PMID 37115694, 2023). "Mechanistically, we reveal that tumor-associated macrophages (TAMs) mediate the stabilization of FGL1 through nuclear factor kappa-B (NF-ĸB) activation and OTU deubiquitinase 1 (OTUD1) expression in the liver microenvironment." (PMID 37872170, 2023). "Here, the authors find tumor-associated macrophages in the liver microenvironment induces elevated secretion of FGL1 from cancer cells and hepatocytes which promotes CRC metastasis by suppressing the infiltration of T cells." (PMID 37872170, 2023). "The results show that loss of FGL1 in MC38 cells significantly suppressed metastatic tumor progression in C57BL/6 J mice, as evidenced by the bioluminescence intensity, liver weight and number of liver metastases." (PMID 37872170, 2023). "FGL1 expression level is associated with epithelial-mesenchymal transition, tumor angiogenesis, proliferation and apoptosis, drug resistance and tumor immune escape." (PMID 38098892, 2023). "We also found that the expression of FGL1 on CTCs was associated with the level of FGL1 in tumor tissues." (PMID 35273912, 2022). "Authors have shown interaction between LAG3 and its receptor FGL1 can cause changes in the tumour microenvironment, such as reduction in IL-2 levels, disrupting anti-tumour immunity." (PMID 35625783, 2022). "FGL1 represses antigen-specific T-cell activation and exerts a tumor immunosuppressive effect, and it is associated with poor prognosis and resistance to anti-PD-1 therapy." (PMID 34458265, 2021). "FGL1 is highly generated by human cancer cells, and elevation of plasma levels of FGL1 in tumor patients is associated with resistance to PD-1/PD-L1 therapy." (PMID 33867830, 2021). "Additionally, in the cancer context, LAG-3 also binds fibrogen-like protein 1 (FGL1) released by cancer cells, galectin-3 on tumor and tumor-associated stroma cells, and LSECtin on tumor cells." (PMID 40075753, 2025). "Fgl1 deficiency or anti-FGL1 mAb blockade restrained liver metastasis and slowed the growth of orthotopic tumors, significantly prolonging the survival of tumor-bearing mice." (PMID 38973608, 2024). "FGL1 was identified as a tumor-associated factor many years ago." (PMID 38098892, 2023). "Noteworthy, FGL1 is positively associated with CD4+ T cell levels within the tumor, while it can also support the expression of CD3D and prevent that of FOXP3; hence, FGL1 may support T cell tumor infiltration and function in the cancer microenvironment." (PMID 36268014, 2022). "Moreover, FGL1 is highly secreted from tumor cells, and higher plasma levels of FGL1 are associated with resistance to ICIs and poor prognosis in cancer patients." (PMID 34526102, 2021). "Interestingly, in contrast to the in vitro assay, our results showed that FGL1 knockdown inhibited orthotopic tumor growth in xenograft tumor model using T cell-deficient nude mice." (PMID 34956878, 2021). "The interaction of LAG3 and FGL1 may cause changes in the tumor immune microenvironment, such as the reduction of IL-2 levels." (PMID 35111155, 2021). "Furthermore, research suggests that elevated levels of FGL1 in circulating tumor cells may be associated with resistance to programmed cell death protein-1 and its ligand PD-L1 (PD-1/PD-L1) immune checkpoint inhibitors." (PMID 38816776, 2024).
tumor (continued). "Furthermore, Fgl1 deficiency or anti-FGL1 mAb blockade restrained liver metastasis and slowed the growth of orthotopic tumors, with significantly prolonged survival of tumor-bearing mice." (PMID 38973608, 2024). "Additionally, multiple other tumor suppressor loci are near FGL1, suggesting that loss of the gene (i.e., via chromosomal damage) may be linked to other tumor suppressor genes." (PMID 37115694, 2023). "USP7 promotes immune suppression by stabilizing checkpoint molecules such as PD-L1, modulating FGL1/LAG-3 signaling, reshaping tumor-associated macrophage polarization, and reinforcing T-cell dysfunction." (PMID 42245660, 2026). "In SGC-7901 cells, FGL1 knockdown significantly promotes the invasion, proliferation, and migration of tumor cells." (PMID 41024301, 2025). "Further, glucose consumption, lactate production, and pyruvate production assays in the four NSCLC cell lines to evaluate the effect of FGL1 on tumor glycolysis revealed significant inhibition of glycolysis after FGL1 knockdown (P < 0.05)." (PMID 41024301, 2025). "Blocking FGL1-LAG-3 interaction can significantly enhance anti-tumor T cell responded and produced synergistic effects with anti-PD-1 therapy, providing a potential target for the development of novel cancer immunotherapies." (PMID 40276056, 2025). "Conversely, FBXO38 restoration enhances tumor sensitivity to anti-FGL1 therapy and amplifies the inflammatory response." (PMID 40534867, 2025). "A549, H226, and LLC cell lines were used for subcutaneous tumor-bearing nude mice, and shFGL1_AAV9 was used for intratumoral injection when the Tumor volume reached 150–200 mm3 to achieve FGL1 knockdown in vivo." (PMID 41024301, 2025). "FGL1 knockdown inhibited tumor progression, including proliferation and metastasis by affecting glycolysis." (PMID 41024301, 2025). "FGL1, which was secreted at low levels in normal liver but was abnormally high expressed in a variety of cancers, inhibits T cell activation and promotes tumor immune escape by binding LAG-3." (PMID 40276056, 2025). "Loss of FBXO38 significantly increases FGL1 abundance, which suppresses CD8+ T cell infiltration, enhances tumor growth, and promotes immune escape." (PMID 40534867, 2025). "The interaction between LAG - 3 and FGL1 leads to T cell exhaustion and impaired proliferation, thereby facilitating tumor progression." (PMID 40977703, 2025). "In vitro characterization experiments were performed to further investigate the function of FGL1 on Tumor proliferation, metastasis, and glycolysis." (PMID 41024301, 2025). "LAG-3 interacts with ligands such as major histocompatibility complex II (MHC-II) expressed by tumor or innate immune cells, and fibrinogen-like protein 1 (FGL-1), highly expressed in some tumors." (PMID 40234667, 2025). "All three cell lines showed that intratumoral inhibition of FGL1 significantly inhibited tumor proliferation (P < 0.05)." (PMID 41024301, 2025). "Our mass spectrometry, transcriptomic, and metabonomic analyses suggest that FGL1 regulates glycolysis by mediating the PI3K/AKT/HIF-1α pathway to influence malignant progression such as tumor proliferation and metastasis." (PMID 41024301, 2025). "Further analyses suggested that FGL1 promotes tumor proliferation, metastasis and lymph tube formation, and finally induces lymph node metastasis, which is verified in vivo and in vitro, whereas its knockdown inhibits these processes." (PMID 41024301, 2025). "Other studies have shown that the deacetylase sirtuin 2 (SIRT2) can stabilise fibrinogen‐like protein 1 (FGL1) protein levels and that FGL1 plays a crucial role in tumour immune evasion." (PMID 39778006, 2025). "FGL1 can negatively regulate the tumor immune microenvironment by inhibiting T cell activation through binding to LAG3." (PMID 41024301, 2025).
tumor (continued). "It is expressed on various immune cells, including NK cells, activated and exhausted T cells, and dendritic cells, and can bind to multiple ligands such as fibrinogen-like protein 1 (FGL1) on tumor cells and MHC-II on antigen-presenting cells." (PMID 40849493, 2025). "FBXO38 ubiquitinates fibrinogen-like protein 1 (FGL1), negatively regulating its stability and thereby inhibiting tumor immune evasion." (PMID 40534867, 2025). "Further analyses suggested that FGL1 promotes tumor proliferation, metastasis, and lymph tube formation, ultimately inducing lymph node metastasis." (PMID 41024301, 2025). "Here, an experimental model of CRC liver metastasis generated by the spleen transfer of MC38-Luc tumor cells was used to explore the role of FGL1 in the liver tumor microenvironment." (PMID 38973608, 2024). "Ieramlimab (LAG525) is a humanized IgG4 monoclonal antibody developed by Novartis that inhibits the interaction between LAG3 and MHC-II, as well as FGL-1, thereby suppressing tumor cell growth." (PMID 39743998, 2024). "In this study, we aimed to investigate the intricate molecular mechanisms underlying the impact of radiation therapy on ESCC, with a specific focus on the role of FGL1 in tumor migration and metastasis." (PMID 38702629, 2024). "Spatial mapping further associates low MC tumor regions with immune escape, mediated by PDGFRB signaling activating the downstream immunosuppressive LAG3/FGL1 axis." (PMID 39015573, 2024). "Then, treatment with KDM4A inhibitor (QC6352) at a dose of 10 mg/kg alone or in combination with FGL1 mAb was administered to tumor-bearing mice." (PMID 39085849, 2024). "Beyond its immunosuppressive role, FGL1 affects tumor processes, such as epithelial-mesenchymal transition (EMT), proliferation, and drug resistance." (PMID 39085849, 2024). "Hepatocyte-derived FGL1 plays critical immunoregulatory roles in the liver and contributes to liver metastasis and tumor growth." (PMID 38973608, 2024). "Remarkably, aspirin has been shown to amplify the effects of PD-L1 blockade in HCC Hepa 1–6 and H22 tumor models by directly acetylating FGL1, facilitating its degradation and offering a potential strategy to enhance HCC immunotherapy." (PMID 38997696, 2024). "This method non-invasively provides tumor-related information, suggesting that FGL1 has significant clinical potential both as a therapeutic target and as a biomarker for efficacy and prognosis in NSCLC." (PMID 39085849, 2024). "Further in vivo experimentation demonstrated that the injection of monoclonal antibodies (McAbs) targeting LAG-3, PD-1, and FGL-1 led to a modest inhibition of tumor growth." (PMID 39331884, 2024). "LAG-3 hinders effective recognition and clearance of tumor cells by NK cells through interaction with FGL1 (fibrinogen-like protein), which is highly expressed in hepatocytes and tumor cells." (PMID 39906665, 2024). "The results confirmed that the application of QC6352 significantly inhibited tumor growth, and the combined treatment with FGL1 mAb showed an even more pronounced inhibitory effect on the tumor." (PMID 39085849, 2024). "We measured the expression levels of FGL1 on circulating tumor cells (CTCs) in 65 patients and found that patients with a dynamic decrease in FGL1 expression on CTCs exhibited a better therapeutic response." (PMID 39085849, 2024). "Recent studies have unveiled elevated FGL1 expression in various malignancies, with heightened levels correlated with increased tumor invasion and metastasis." (PMID 38702629, 2024). "First, WT mice were pretreated with anti-FGL1 mAb 1 day before tumor cell inoculation by using a CRC liver metastasis model of MC38 tumor cells and a liver orthotopic tumor model of Hepa1-6 tumor cells." (PMID 38973608, 2024). "Reducing FGL1 levels by oxysophocarpine or aspirin treatment sensitized HCC cells to anti–LAG-3 or anti–PD-L1 immunotherapy in the subcutaneous tumor model." (PMID 38973608, 2024).